NOTCH3 (notch receptor 3)
Diseases named in the same sentence as NOTCH3 in open-access papers (continued):
Sharing a sentence is not in itself a finding about the gene and the disease.
Stroke (continued). "Altered NOTCH3 activity has also been linked to age-dependent small vessel disease which, like CADASIL is linked to impaired VSMCs and is an important contributor to stroke and vascular dementia, the latter comprising around 20% of all dementia diagnoses." (PMID 40764588, 2025). "In this context, the discussion will delve into the patient's clinical course, the significance of neuroimaging in confirming the diagnosis, the genetic confirmation through NOTCH3 testing, and the multidisciplinary approach involving stroke and neurology teams for effective management." (PMID 39507177, 2024). "In keeping with this LOF hypothesis, genetic invalidation of Notch3 in the mouse leads to arterial SMC loss in the cerebro-retinal vasculature and increased susceptibility to stroke." (PMID 38386425, 2024). "We enrolled 81 individuals with NOTCH3 cysteine-altering variants (mean age = 57.2 ± 13.1 years, males/females = 36/45), including 37 preclinical carriers, and 44 symptomatic CADASIL patients who manifested with stroke or cognitive decline." (PMID 38162905, 2024). "TIMP-3 forms complexes with NOTCH-3 and accumulates in the extracellular matrix of brain vessels of patients and mice with CADASIL, an inherited cerebral small vessel disease and a cause of stroke and dementia." (PMID 35629249, 2022). "Family of origin did not alter the effect of NOTCH3 variant position on age at stroke onset (i.e., with the inclusion of only 1 patient per family in our analysis, similar results were found)." (PMID 35641310, 2022). "NOTCH3 variant position is a predictor of stroke and encephalopathy in CADASIL independent of cardiovascular risk factors." (PMID 35641310, 2022). "NOTCH3 EGFr group is the most important CADASIL disease modifier not only for age at first stroke and WMH volume but also strikingly so for a whole battery of clinically relevant disease measures such as lacune volume and peak width of skeletonized mean diffusivity." (PMID 35862191, 2022). "In conclusion, our study confirms that NOTCH3 variant position is a predictor of disease severity, particularly regarding the age at onset of stroke, and this is independent of conventional cardiovascular risk factors." (PMID 35641310, 2022). "Despite that intracerebral hemorrhage (ICH) is considered a rare manifestation in Caucasian CADASIL patients, a significant proportion of East Asian patients harboring p.R544C NOTCH3 mutation also suffer from ICH, and those with ICH are more prone to have recurrent stroke." (PMID 32321529, 2020). "NOTCH3 pathogenic variant position is the most important determinant of CADASIL disease severity, with EGFr 7–34 pathogenic variant predisposing to a later onset of stroke and longer survival." (PMID 30032161, 2019). "In contrast, a study based on an Austrian population without stroke showed that NOTCH3 variants were associated with the presence and progression of WMH35." (PMID 30692550, 2019). "The two reported Notch3 knockout mouse models are susceptible to stroke when challenged, but no other neural deficits have been reported." (PMID 23720232, 2013). "Notably, the resting cerebral blood flow (CBF) in both Notch3 mice was normal, but middle cerebral artery occlusion led to an exacerbated stroke phenotype." (PMID 23720232, 2013). "Early-onset, presence of family history of stroke, external capsule lesions, and absence of hypertension may help predict underlying NOTCH3 mutations despite no temporal white matter lesions." (PMID 32477100, 2020). "None of the NOTCH3 mutation carriers had a history of clinical strokes (although 1 carrier had multiple infarcts shown on magnetic resonance imaging and a history of diabetes and cardiovascular disease) and all had prominent memory impairment as the initial presentation with a progressive course." (PMID 30924900, 2019). "Besides, a younger age of stroke onset has been reported in the NOTCH3 C174Y mutation, and a worse profile of WMLs has been noted in the C440G mutation." (PMID 26308724, 2015).
Stroke (continued). "In the data set of clinically ascertained NOTCH3lof cases, ascertainment bias has likely contributed to a higher reported stroke incidence because in the clinical setting, only patients with a CADASIL-like phenotype will receive NOTCH3 genetic testing." (PMID 40882175, 2025). "Two patients (cases 8 and 10) with vascular Notch3 ECD deposits had neither lesion in the temporal pole on MRI nor a family history of stroke." (PMID 35775048, 2022). "The effect of NOTCH3 PV position on age at first stroke was not influenced by family of origin (i.e., when including only one individual per family, similar results were found)." (PMID 30032161, 2019). "Reduced expression of sGC, correlating with differential expression of MAML2, in stroke prone and spontaneously hypertensive rats was also seen, and RNA-Seq data demonstrated correlations between JAG1, NOTCH3, MAML2 and FRYL and the sGC subunits GUCY1A3 and GUCY1B3 in human coronary artery." (PMID 28465505, 2017). "This mutation, which also affects the number of cysteines in NOTCH3-ECD, is particularly interesting as patients carrying a NOTCH3C455R germline mutation experience severe CADASIL with early stroke onset (median age = 31 years) and widespread white-matter defects." (PMID 39537978, 2025). "Therefore, NOTCH3 gene screening criteria should not be restricted to patients with high risk for CADASIL, especially those without typical imaging findings but presenting with early-onset stroke, a family history of stroke or dementia, and no hypertension." (PMID 40470487, 2025). "Vascular NOTCH3 protein accumulation could be an interesting therapeutic biomarker for CADASIL, as increased vascular NOTCH3 staining and GOM are consistently found in skin arterioles of pre-symptomatic patients, decades before onset of stroke and cognitive decline." (PMID 26715087, 2015).
Leukoencephalopathy (64 papers, 2010 to 2026). This term describes abnormality of the white matter of the cerebrum resulting from damage to the myelin sheaths of nerve cells. "Their study highlighted the pathogenic nature of the NOTCH3 c.1672C > T (p.Arg558Cys) genotype, associated with cerebral autosomal dominant arteriopathy with subcortical infarcts and leukoencephalopathy." (PMID 41379817, 2025). "The results showed that WES combined with dynamic mutation analysis increased the diagnostic rate to 48.1% in the leukoencephalopathy cohort, with NOTCH3 and NOTCH2NLC being the most commonly mutated genes." (PMID 37237429, 2023). "Cerebral autosomal dominant arteriopathy with subcortical infarcts and leukoencephalopathy is exclusively caused by mutations in the NOTCH3 gene." (PMID 36524456, 2023). "NOTCH3 (Notch Receptor 3) is the best known of these genes and is implicated in cerebral autosomal dominant arteriopathy with subcortical infarcts and leukoencephalopathy." (PMID 35699195, 2022). "In human patients, mutations in Notch3 are associated with the pathogenesis of cerebral autosomal dominant arteriopathy with subcortical infarcts and leukoencephalopathy, a condition that leads to breakdown of the BBB and is associated with dementia." (PMID 35969789, 2022). "NOTCH3 gene mutations predominantly cause cerebral autosomal dominant arteriopathy with subcortical infarcts and leukoencephalopathy, a common etiology of subcortical vascular dementia (SVaD)." (PMID 33942994, 2021). "Cerebral autosomal dominant arteriopathy with subcortical infarcts and leukoencephalopathy, which is caused by mutations of the NOTCH3 gene, has a large heterogeneous progression, presenting with declines of various clinical scores and occurrences of various clinical event." (PMID 38105268, 2023). "It is also notable that across several monogenic cSVDs, WMLs were commonly identified in the temporal region, a feature that has previously been associated with cerebral autosomal dominant arteriopathy with subcortical infarcts and leukoencephalopathy (caused by NOTCH3 mutations)." (PMID 35699195, 2022). "More recently, a homozygous NOTCH3 nonsense mutation was identified in a patient who exhibited livedo reticularis from birth and childhood-onset cavitating leukoencephalopathy with multiple deep lacunar infarcts, disseminated microbleeds and two saccular aneurysms of middle cerebral arteries." (PMID 32980981, 2021). "CADASIL (cerebral autosomal dominant arteriopathy with sub-cortical infarcts and leukoencephalopathy) is an inherited form of cerebrovascular disease that is associated with changes in the number of cysteines causing an odd number of cysteines in the mutant NOTCH3." (PMID 35207132, 2022). "Finally, mutations in the NOTCH3 gene cause various abnormalities, including arteriopathy and leukoencephalopathy, which occur also (to various degrees) in MPS, thus suggesting that the dysregulation of expression of this gene may be connected to MPS symptoms." (PMID 35456399, 2022). "All the patients of whom neuroimaging was available (46/50) present with brain small vessel disease and leukoencephalopathy, characteristic hallmarks of NOTCH3-SVD." (PMID 39191170, 2024). "These include CADASIL (due to mutations in the NOTCH3 gene) and CARASIL (cerebral autosomal recessive arteriopathy with subcortical infarcts and leukoencephalopathy, due to mutations in the HTRA1 gene)." (PMID 37396778, 2023). "Our findings here are consistent with previous studies linking NOTCH3 to IA, and cerebral autosomal dominant arteriopathy with subcortical infarcts and leukoencephalopathy." (PMID 31339861, 2019). "Mutations in the human NOTCH3 gene cause CADASIL syndrome (cerebral autosomal dominant arteriopathy with subcortical infarcts and leukoencephalopathy)." (PMID 23720232, 2013).
Leukoencephalopathy (continued). "Cerebral autosomal dominant arteriopathy with subcortical infarcts and leukoencephalopathy shares a number of features with AD, including that both are considered protein misfolding and aggregation diseases and that both NOTCH3 and Aβ aggregates accumulate in the extracellular milieu." (PMID 36524456, 2023). "The major differential diagnosis of leukoencephalopathies includes the inherited cerebral vasculopathies, such as cerebral autosomal dominant arteriopathy with subcortical infarcts and leukoencephalopathy (CADASIL), caused by NOTCH3 mutations." (PMID 38132285, 2023). "Cerebral autosomal-dominant arteriopathy with subcortical infarcts and leukoencephalopathy is the most common hereditary CSVD, which is caused by a mutation of cysteine-altering in the NOTCH3 gene on chromosome 19, mainly due to mutations in the NOTCH3 extracellular domain (NOTCH3 ECD)." (PMID 36119691, 2022). "This patient may have a new type of mutation that is different from the one seen in cerebral autosomal dominant arteriopathy with subcortical infarcts and leukoencephalopathy, although it involves a NOTCH3 defect." (PMID 31441874, 2019). "Differences between LoF and cysteine-involving missense variants provide evidence supporting the genotype-phenotype variability of NOTCH3-SVD, all of which are characterised by small vessel involvement in the brain leading to leukoencephalopathy and subcortical strokes." (PMID 39191170, 2024). "A CADASIL (Cerebral autosomal dominant arteriopathy with subcortical infarcts and leukoencephalopathy; OMIM #125310) was suspected but NOTCH3 gene testing was negative." (PMID 29364180, 2018).
lung carcinoma (57 papers, 2011 to 2025). "The treatment of EGFR-mutated lung cancer cell lines with erlotinib enriched then stem-like cells with stem-like cell potential through EGFR-dependent activation of NOTCH3." (PMID 35584089, 2022). "In vitro, there is evidence that down-regulation of NOTCH3 is associated with reduced cell proliferation and cell motility in human lung cancer cell lines." (PMID 35538551, 2022). "According to numerous reports, notch-3 is associated with the development of cancer, including lung cancer." (PMID 35118116, 2021). "We then asked what would be the consequence of an upregulation of Notch3 in these cells that would mimic the aberrant expression of Notch3 observed in lung cancers-associated endothelial cells." (PMID 28719575, 2017). "In lung cancer cell lines, NOTCH3 was highly expressed and associated with karyotypic abnormalities." (PMID 27938406, 2016). "In complementary, Dr. Carbone’s group found that treatment of EGFR-mutated lung cancer cell lines with erlotinib enriched the ALDH+ stem-like cells with stem-like cell potential through EGFR-dependent activation of Notch3." (PMID 25477004, 2014). "Overexpression of Notch3 was found to be associated with chromosome 19 translocation in lung cancer." (PMID 23688269, 2013). "In lung cancer, Notch3 has been reported to be associated with poor prognosis." (PMID 35118116, 2021). "Targeting TANs with Notch3 could be a new diagnostic and therapeutic strategy for treating lung cancer." (PMID 35118116, 2021). "Previous reports have shown that Notch3 has a certain promoting effect on the occurrence, development, and metastasis of lung cancer." (PMID 38342606, 2024). "Among the 20E-down-regulated genes in lung cancer cells, several of them are considered to be oncogenes, including Notch3, HSF1, mTOR, SOX12, KLF16 (Kruppel-like factor 16,), and others." (PMID 37233697, 2023). "Of the fringes, MFNG acts as a tumor suppressor in lung cancer by inhibiting the activation of Notch3." (PMID 35804829, 2022). "Notch3 can promote colony formation and sphere formation of stem-like capacity in lung cancer cells, and high expression of Notch3 was related to a poor outcome of patients with NSCLC." (PMID 35993327, 2022). "NOTCH3 overexpression has been reported to be responsible for increased in vitro tumor cell growth in human lung cancer and NOTCH3 constitutive activation was reported to inhibit terminal differentiation in lungs of transgenic mice." (PMID 36556190, 2022). "Here, autophagy was also activated in drug-resistant lung cancer cells, thus postulating a critical role of Notch3 not only in enhancing the stem-like properties but also in the activation of autophagy." (PMID 35053430, 2022). "The results showed that BH significantly suppressed excessive Notch3 signaling and displayed potent antitumor activity against human lung cancer cell xenograft models." (PMID 35463301, 2022). "Taken together, combining a Notch3 inhibitor with gefitinib inhibits the growth of TKI-resistant lung cancer xenografts more effectively than either treatment separately." (PMID 35463301, 2022). "A current study found that chemoresistant NSCLC patients had upregulated Notch3 expression, which was related to poor prognosis and had augmented levels of CSC markers, ALDH1A1 and CD44, correlating with Notch3 expression in lung cancer biopsies." (PMID 35053430, 2022). "We further investigated the activation of neutrophils by supernatant of cultured lung adenocarcinoma cells and the effect of these TANs on the migration and invasion of lung cancer cells via the Notch3 pathway." (PMID 35118116, 2021). "Results from our in vitro experiments demonstrated that TANs increased the expression of Notch3 in lung cancer cells." (PMID 35118116, 2021). "We further noted inhibition of the migration and invasion of lung cancer cells mediated by TANs after the knockdown of Notch3." (PMID 35118116, 2021).
lung carcinoma (continued). "Subsequent to the first report of IGF-1R activation in 2010, AXL, Notch3, and fibroblast growth factor receptor 3 (FGFR3) are identified as receptor tyrosine kinases (RTKs) that cause drug tolerance in lung cancers with EGFR mutations." (PMID 34202566, 2021). "To verify this, we detected the expression of Notch3 in lung cancer by immunohistochemical staining and analyzed its correlation with TANs." (PMID 35118116, 2021). "Our findings suggest an interaction between Notch3 and neutrophils in the lung cancer tumor microenvironment." (PMID 35118116, 2021). "Subsequent work showed that EGFR TKI activation of Notch 3 in EGFR-mutant lung cancer cells is accompanied by stabilisation and activation of β-catenin." (PMID 32575680, 2020). "Two human NSCLC cell lines with constitutively active NOTCH3, A549 and H1299, and the urethane-induced lung cancer mice model were employed in this study." (PMID 29765324, 2018). "A DNA methyltransferase inhibitor was employed to investigate the role of NOTCH3 signaling in the anti-lung cancer effects of EVO." (PMID 29765324, 2018). "In this study, we explored the involvement of NOTCH3 signaling in the anti-lung cancer effects of EVO." (PMID 29765324, 2018). "In summary, we demonstrate that a novel NOTCH3 methylation stimulator EVO exerts anti-lung cancer activities and inhibits NOTCH3 signaling." (PMID 29765324, 2018). "Detection of the level of DNA methylation (e.g., NOTCH3 methylation) is expected to be an important approach for early diagnosis of lung cancer." (PMID 29765324, 2018). "Here, we analyzed the relationship between NOTCH3 and lung cancer using TCGA, Kaplan–Meier and MethHC databases." (PMID 29765324, 2018). "Collectively, EVO, a novel NOTCH3 methylation stimulator, exerted potent anti-lung cancer effects partially by inhibiting NOTCH3 signaling." (PMID 29765324, 2018). "We next injected LLC1 syngeneic lung cancers cells in Notch3+/LacZ to assess expression of Notch3 in subcutaneous graft." (PMID 28719575, 2017). "It has been published that inhibition of Notch3 signaling suppresses cell growth and induces apoptosis in breast, ovarian and lung cancers." (PMID 29069826, 2017). "Notch3 potentially contributes to the multistep evolution of lung cancer in airway epithelium by using a transgenic mouse model." (PMID 28061457, 2017). "We first investigated Notch3 expression in a small panel of human lung cancers by immunohistochemistry." (PMID 28719575, 2017). "NOTCH3 was located in chromosome 19 nearing the breakpoint and suggested to be over-expressed in lung cancer." (PMID 27938406, 2016). "Previous reports showed that Notch2 or Notch3 are involved in gastric carcinogenesis or lung cancer progression." (PMID 26416455, 2015). "In experimental study, either dominant-negative Notch3 receptor or MRK-003, a gamma-secretase inhibitor, antagonized Notch3 signaling, attenuated cell growth, and induced apoptosis of lung cancer cell lines." (PMID 25477004, 2014). "The present study aimed to investigate the expression of Notch3 in adult lung cancer patients and its role in the pathogenesis of primary bronchiogenic carcinoma." (PMID 23420695, 2013). "The expression of Notch3 in the lung cancer tissue was detected by RT-PCR and western blot analysis." (PMID 23420695, 2013). "CHIR99021 considerably inhibited the expression of caspase-3 in H460 cells and Notch3-shRNA increased the expression of caspase-3 in all three lung cancer cell lines." (PMID 24367688, 2013). "The expression of Notch3 in the lung adenocarcinoma group was the highest of the three lung carcinoma groups (P<0.01)." (PMID 23420695, 2013). "Among the three groups of lung cancer specimens, the expression of Notch3 in lung adenocarcinoma was the highest." (PMID 23420695, 2013). "Previous studies concerned with the pathogenesis of lung cancer have identified that Notch3 played an essential role in NSCLC." (PMID 24367688, 2013).